OSTM1 (osteoclastogenesis associated transmembrane protein 1)
Description:
Required for osteoclast and melanocyte maturation and function.
Synonyms: GL; HSPC019; GIPN; OPTB5
Tractability: Small molecule: a structure with a bound ligand is known. Antibody: UniProt predicts a signal peptide or a membrane-spanning region. PROTAC: ubiquitination databases record sites on it; its protein half-life has been measured.
Gene: Protein-coding gene on chromosome 6 (108,029,245 to 108,165,854, reverse strand). Ensembl gene ENSG00000081087.
Subcellular location: Lysosome membrane
Subcellular location (Human Protein Atlas): Cytosol; Nucleoplasm; Vesicles
Pathways (Reactome):
Transport of small molecules: Stimuli-sensing channels
Gene Ontology:
Molecular function: protein binding
Biological process: transepithelial chloride transport; osteoclast differentiation
Cellular component: chloride channel complex; lysosomal membrane; cytosol
Genetic constraint (gnomAD): Loss-of-function variants: 14 observed, 15.33 expected, observed/expected ratio (o/e) 0.91, 90% interval 0.6 to 1.42. The synonymous counts are far from expectation, so gnomAD's model fits this gene poorly and the ratio says little. Missense variants: 249 observed, 241.05 expected, observed/expected ratio (o/e) 1.03, 90% interval 0.93 to 1.15. Synonymous variants: 137 observed, 105.86 expected, observed/expected ratio (o/e) 1.29, 90% interval 1.13 to 1.49.
Gene-disease validity (ClinGen):
ClinGen rates the evidence that OSTM1 causes each of these diseases.
autosomal recessive osteopetrosis 5 (autosomal recessive): Definitive.
Homologues: Orthologues: chimpanzee OSTM1 (99% identical), macaque OSTM1 (99% identical), rabbit OSTM1 (89% identical), dog OSTM1 (87% identical), guinea pig OSTM1 (87% identical), pig OSTM1 (86% identical), rat Ostm1 (80% identical), mouse Ostm1 (78% identical), tropical clawed frog ostm1 (40% identical), zebrafish ostm1 (36% identical), Caenorhabditis elegans cup-15 (19% identical), Drosophila melanogaster CG14969 (19% identical).
Diseases named in the same sentence as OSTM1 in open-access papers:
OSTM1 is named in the same sentence as 20 diseases in open-access papers, as found by Europe PMC text mining. Sharing a sentence is not in itself a finding about the gene and the disease. The quoted sentences say what the papers report.
osteopetrosis (31 papers, 2013 to 2025). Osteopetrosis, also known as marble bone disease, is a descriptive term that refers to a group of rare, heritable disorders of the skeleton characterized by increased bone density on radiographs. "In summary, nefarious multisystemic effects of malignant infantile osteopetrosis, especially those with OSTM1 mutations, are illustrated in this case." (PMID 40625472, 2025). "Surprisingly, the same approach failed when TRAP promoter-mediated Ostm1 expression was applied to rescue osteopetrosis in gray lethal (gl) mice which also displayed neuronal loss." (PMID 37374100, 2023). "Accordingly, impaired bone resorption in osteoclast, caused by a functionally defective ClC-7/Ostm1 complex, causes osteopetrosis, a disease characterized by stiff and fragile bones." (PMID 37374100, 2023). "Mutations in OSTM1 (transmembrane protein 1associated with osteopetrosis) account for about 5 % ofARO cases and invariably cause osteopetrosis and severeprimary neurodegeneration with a life expectancy of lessthan two years." (PMID 37465191, 2023). "Loss of ClC-7 or Ostm1 leads to osteopetrosis accompanied by accumulation of storage material in lysosomes and neurodegeneration." (PMID 38136669, 2023). "A study proposed that OSTM1 mutation leads to severe osteopetrosis by disrupting Wnt/β-catenin signaling." (PMID 37373559, 2023). "Further evidence came from the identification of a spontaneous Ostm1 mutation to be associated with the onset of a severe osteopetrosis in gray lethal mice presenting a fur color defect." (PMID 37374100, 2023). "Mutations in ClC-7 and Ostm1 cause osteopetrosis, but also a form of lysosomal storage disease and neurodegeneration, consistent with the phenotype of ClC-7 and Ostm1 loss-of-function mouse models." (PMID 35159175, 2022). "OSTM1 mutations cause an osteoclast-rich, severe form of osteopetrosis with mild to severe hematological, ocular and growth defects." (PMID 34753502, 2021). "Mutations in ClC-7 and the associated Ostm1 underlie osteopetrosis due to its role in osteoclast bone resorption and to impaired skin pigmentation." (PMID 33708769, 2021). "As a member of the chloride channel family, there was a missense mutation in CLCN7 gene, accelerating the gating of the lysosomal Cl−/H−exchanger ClC-7/Ostm1, causing osteopetrosis with gingival hamartomas in cattle." (PMID 35011147, 2021). "Additional OSTM1 mutations with severe osteopetrosis also displayed neurological disorders suggesting that Ostm1 activity can be essential in maintenance of neuronal cell homeostasis." (PMID 32764302, 2020). "Similar to Ostm1, the loss of ClC-7 leads to osteopetrosis in mice and humans with neuronal defects and retinal degeneration." (PMID 32764302, 2020). "Kif5B binds to and functions in lysosomal trafficking of Osteopetrosis Associated Transmembrane Protein 1 (Ostm1), a gene associated with osteopetrosis in humans, connecting Kif5B to cartilage/bone development." (PMID 28715414, 2017). "In spite of normal lysosomal pH, lysosomal degradation of endocytosed protein is impaired in ClC-7/Ostm1-deficient mice, which develop a neurodegenerative lysosomal storage disease in addition to osteopetrosis." (PMID 24159188, 2014). "To date, only four different human OSTM1 mutations have been identified, always leading to recessive malignant osteopetrosis." (PMID 23160729, 2013). "Grey-lethal (gl) mice have a recessive null mutation in Ostm1 that leads to a grey coat colour and early lethality due to severe osteopetrosis." (PMID 23160729, 2013). "An OSTM1 mutation causes the most severe classification of osteopetrosis, OPTB5." (PMID 37373559, 2023). "Mutations in either ClC-7 or Ostm1 result in osteopetrosis in human patients and animal models." (PMID 38136669, 2023). "Besides osteopetrosis, ClC-7 and Ostm1 deficient mice also have a pigmentation phenotype, which also indicates an additional physiological role." (PMID 35159175, 2022).
osteopetrosis (continued). "Less frequent osteopetroses (5% of ARO cases) present mutations in the osteoclastogenesis-associated transmembrane protein 1 (OSTM1) gene, encoding a highly glycosylated protein at its N-terminus able to stabilize ClC-7 and complement its activity at the ruffled border." (PMID 33970241, 2021). "The osteopetrotic phenotype of the grey-lethal (gl) mouse as well as a variant of severe autosomal recessive infantile malignant osteopetrosis were both caused by a gene defect in the mouse Ostm1 and human OSTM1 gene resulting in a partial deletion leading to a null allele." (PMID 33086479, 2020). "Here, we summarize the steps toward isolation and characterization of the osteopetrosis associated trans-membrane protein 1 (Ostm1) gene and protein, essential for proper osteoclast maturation, and responsible when mutated for the most severe form of osteopetrosis in mice and humans." (PMID 32764302, 2020). "Myotonia congenita, leukodystrophy, Bartter syndrome, Dent’s disease, and osteopetrosis/retinal degeneration/lysosomal storage disease have well-established association with loss-of-function of ClC1, ClC-2, ClC-K/Barttin, ClC-5 and ClC-7/Ostm1, respectively." (PMID 28386229, 2017). "Mutations in OSTM1 (osteopetrosis associated transmembrane protein 1), coding for a protein involved in transport of ClCn7 to the ruffled border (and considered as a β subunit of ClCn7), have been described as causing severe osteopetrosis in ~5% of patients." (PMID 25873953, 2015). "Because it is unknown whether these mutations also decrease ClC-7/Ostm1 protein levels in patients, it remained unknown whether the acceleration of ClC-7 is causative for osteopetrosis." (PMID 24159188, 2014). "Ostm1 mutations have been identified in mouse and human as causing very severe osteopetrosis." (PMID 23160729, 2013). "While we suspect that alterations in acidification machinery (e.g., CLC transporters) contribute to the significant loss of resorptive remodeling in osteopetrotic bones, we hypothesized that hyperfusion also contributes to the loss of resorptive function in SNX10- and OSTM1-linked osteopetrosis." (PMID 40964326, 2025). "The acceleration by a factor of about three is comparable with that of other mutations that accelerate ClC-7/Ostm1 gating by a factor between ~2.5 and >5 and is clearly stronger than the less-than-twofold acceleration by a recently identified human ClC-7 mutation causative for osteopetrosis." (PMID 24159188, 2014). "Whole-exome sequencing revealed malignant infantile osteopetrosis based on a homozygous deletion in the OSTM1 gene." (PMID 40625472, 2025). "In spite of these efforts, the clinical course continued to be relentlessly progressive, which is characteristic of the natural history of OSTM1-related osteopetrosis." (PMID 40625472, 2025). "Whole-exome sequencing identified malignant infantile osteopetrosis (type 5) with a homozygous OSTM1 deleted gene." (PMID 40625472, 2025). "For example, Sanjad–Sakati syndrome (hypoparathyroidism–retardation–dysmorphism syndrome) and OSTM1-related osteopetrosis are almost exclusively seen in GCC countries, and their management is mainly limited to palliation." (PMID 36910455, 2023). "OSTM1 is predicted to be a glycosylated, single-pass transmembrane protein and mutations in OSTM1, like mutations in CLC-7, can lead to osteopetrosis and neurodegeneration in humans and mice." (PMID 32749217, 2020). "The characterization of the molecular mechanisms of Ostm1 was of fundamental importance for our understanding of osteoclast biology, but also of high clinical relevance for bone diseases like osteopetrosis." (PMID 32764302, 2020). "This latter phenotype was most likely not a secondary effect due to excess bone accumulation and cranial nerve compression described in some osteopetrosis forms but rather suggests an intrinsic neuronal role of Ostm1 that will be further analyzed." (PMID 32764302, 2020).
osteopetrosis (continued). "OSTM1 (osteopetrosis-associated transmembrane protein 1) mutations are reported in 5% of ARO cases and invariably cause osteopetrosis and severe primary neurodegeneration, with a life expectancy lower than 2 years." (PMID 30837952, 2019). "Recently, an accelerated gating kinetics of the lysosomal Cl/H-exchanger ClC-7/Ostm1 has been brought up as the reason for osteopetrosis with gingival hamartomas in cattle." (PMID 26042048, 2015). "Two of the genes whose mutations cause osteopetrosis are CLCN7 and OSTM1, encoding the chloride-proton (Cl−/H+) exchanger ClC-7 and its obligate β-subunit Ostm1 (osteopetrosis-associated transmembrane protein 1)." (PMID 24159188, 2014). "Like several human osteopetrosis-associated CLCN7 mutations, the present bovine CLCN7 mutation drastically accelerated ClC-7/Ostm1 gating." (PMID 24159188, 2014). "Our successful quest to understand the mouse grey-lethal osteopetrotic mutation was a long journey but it has allowed us to characterize the previously unknown Ostm1 locus responsible for the most severe form of osteopetrosis in mice and humans." (PMID 32764302, 2020). "Importantly, targeted early re-expression of Ostm1 in hematopoietic cells of transgenic mice with the regulatory sequences of the transcriptional factor gene PU.1 (PU.1-Ostm1) resulted in full rescue of osteopetrosis and hematopoietic defects." (PMID 32764302, 2020). "Interestingly, dysfunction of lysosomal ClC-7/Ostm1 also results in a neuronal pathology that cannot be treated by bone marrow transplantation, the usual treatment for osteopetrosis." (PMID 24159188, 2014). "Therefore, the precise function of the ClC-7/Ostm1 complex and its relative contribution to the pathogenesis of osteopetrosis are important questions." (PMID 24159188, 2014). "Mice lacking either ClC-7 or Ostm1 develop a lysosomal storage disease and mutations in either protein have been found to underlie osteopetrosis in mice and humans." (PMID 24159188, 2014). "Various forms of recessive osteopetrosis have been reported, some of which are associated with the most severe phenotypes (including those caused by mutations in the TCIRG1, CLC7, and OSTM1 genes), whereas mutations in other genes (CAII and PLEKHM1) give a milder osteopetrotic phenotype." (PMID 23160729, 2013). "In support of the key involvement of OSTM1 in LRRK1 signal pathways are the findings that both OSTM1 and CLC7 play a critical role in regulating osteoclast function by providing extracellular acidification and ablation of either Ostm1 or Clc7 in mice, causing severe osteopetrosis." (PMID 37106712, 2023). "Therefore, Ostm1 expression in mature osteoclasts is absolutely required to prevent osteopetrosis." (PMID 32764302, 2020). "However, ClC-7 null mice display a milder form of osteopetrosis compared to Ostm1, therefore suggesting that Ostm1 may have additional functions." (PMID 32764302, 2020). "Hence, dysfunction of ClC-7/Ostm1 leads to osteopetrosis in mice and humans." (PMID 24159188, 2014). "Although the acceleration of ClC-7/Ostm1 that we observed previously with several pathogenic human mutations is intriguing, we could not exclude the possibility that these mutations caused osteopetrosis by reducing ClC-7 protein levels in vivo." (PMID 24159188, 2014). "In contrast to other gene defects described in osteopetrosis (TCIRG1, CLCN7), OSTM1 mutations are typically not curable by a curative hematopoietic stem cell transplantation because of their early and irreversible neurological involvement." (PMID 40625472, 2025). "Mutations in genes TCIRG1, CLCN7, OSTM1, SNX10 and PLEKHM1 lead to osteoclast rich osteopetrosis, which has abundant but nonfunctional osteoclasts." (PMID 34753502, 2021). "Mutations in OSTM1, SNX10, and PLEKHM1 are rare and are also associated with forms of osteopetrosis characterized by the presence of non-functional osteoclasts (osteoclast-rich osteopetrosis)." (PMID 33081155, 2020).
osteopetrosis (continued). "In this study, an affected girl with osteopetrosis was introduced who had no mutation in most common causative genes (TCIRG1, CLCN7 and OSTM1) for the disease, but analysis of SNX10 gene was able to detect a novel homozygous deletion in her." (PMID 29090071, 2017). "At least in mice, dysfunction of ClC-7/Ostm1 additionally leads to a neuronal ceroid lipofuscinosis (NCL)-like lysosomal pathology, and a severe form of osteopetrosis is accompanied by neurodegeneration and accumulation of ceroid lipofuscin in humans." (PMID 24159188, 2014). "The lack of OSTM1 vesicles linked to KIF5B cargos caused an absence of lysosomes on the ruffled border, resulting in dysfunctional secretion, inefficient bone resorption, and osteopetrosis." (PMID 37106712, 2023).
autosomal recessive osteopetrosis (3 papers, 2020 to 2024). An autosomal recessive form of osteopetrosis caused by mutation(s) in at least 8 genes related to osteoclast function. "Genetic testing revealed a homozygous variant of OSTM1 gene, which is a known Saudi mutation of autosomal recessive osteopetrosis (ARO)." (PMID 32015934, 2020).
gastric cancer (1 paper, 2025). A primary or metastatic malignant neoplasm involving the stomach. "Osteoclastogenesis-associated transmembrane protein 1 (OSTM1), a transmembrane protein overexpressed in various tumors, has unclear functions in gastric-cancer progression." (PMID 39852172, 2025). "The results demonstrate that high expression of OSTM1 in gastric-cancer tissues is significantly associated with the invasiveness and metastatic potential of gastric cancer, and this effect may be mediated through the regulation of the S100A4 signaling pathway." (PMID 39852172, 2025). "Firstly, our study found that the expression level of OSTM1 in gastric-cancer tissue samples was significantly higher than that in normal gastric tissues, which is consistent with previous reports." (PMID 39852172, 2025). "Particularly, how OSTM1 influences gastric-cancer cell proliferation and metastasis through the regulation of the S100A4 signaling pathway has rarely been reported in the literature." (PMID 39852172, 2025). "This study aims to investigate how OSTM1 promotes gastric-cancer proliferation and metastasis by enhancing the S100A4 signaling pathway." (PMID 39852172, 2025). "To study the effect of OSTM1 on the in vivo tumorigenic ability of gastric-cancer cells, we injected MGC803 cells with OSTM1 knockdown into nude mice via the tail vein and observed lung metastasis." (PMID 39852172, 2025). "Our study reveals the oncogenic role of OSTM1 in gastric cancer, which is consistent with previous reports in other tumors." (PMID 39852172, 2025). "In this study, we investigated the role of OSTM1 in gastric-cancer proliferation and metastasis through the enhancement of the S100A4 signaling pathway." (PMID 39852172, 2025). "The IHC staining revealed that OSTM1 was predominantly localized in the cytoplasm of gastric-cancer cells." (PMID 39852172, 2025). "This ability to “educate” surrounding cells is an important aspect of tumor microenvironment regulation and is one of the potential mechanisms by which OSTM1 promotes gastric-cancer development." (PMID 39852172, 2025). "In nude mouse models, gastric-cancer cells with high OSTM1 expression also exhibited stronger tumorigenic and metastatic capabilities." (PMID 39852172, 2025). "By detecting the expression of OSTM1 in gastric-cancer tissues and adjacent tissues using immunohistochemical staining, we found that the expression of OSTM1 in gastric-cancer tissues was significantly higher than that in the adjacent normal tissues." (PMID 39852172, 2025). "It mediates the regulation of OSTM1 on the invasive ability of gastric-cancer cells and the chemotactic effect of OSTM1-overexpressing gastric-cancer cells on fibroblasts." (PMID 39852172, 2025). "The role of OSTM1 in gastric-cancer development should be investigated using genetically engineered mouse models." (PMID 39852172, 2025). "OSTM1 promotes gastric-cancer progression by upregulating S100A4 and modifying the tumor microenvironment through enhanced angiogenesis and fibroblast activation." (PMID 39852172, 2025). "In summary, our study reveals the key role of OSTM1 in promoting gastric-cancer proliferation and metastasis by enhancing the S100A4 signaling pathway, providing new insights for molecular targeted therapy of gastric cancer." (PMID 39852172, 2025). "S100A4, as a key factor promoting tumor invasion and metastasis, is regulated by OSTM1, providing new clues and potential therapeutic targets for elucidating the mechanism of gastric-cancer metastasis." (PMID 39852172, 2025). "Through this study, we discovered that osteoclastogenesis-associated transmembrane protein 1 (OSTM1) is highly expressed in gastric-cancer tissues, and its expression level is closely related to the clinical staging and prognosis of gastric-cancer patients." (PMID 39852172, 2025). "This suggests that the expression level of S100A4 affects the regulatory effect of OSTM1 on the invasive ability of gastric-cancer cells." (PMID 39852172, 2025).